EGFR (epidermal growth factor receptor)
Diseases named in the same sentence as EGFR in open-access papers (continued):
Sharing a sentence is not in itself a finding about the gene and the disease.
tumor (continued). "When CA XII was assessed as a continuous variable, there was a strong correlation between CA XII expression and tumour grade (r=−0.39, P<0.0001 Spearman's test), ER level (r=0.53, P<0.0001), EGFR (r=−0.38, P<0.0001) and extent of necrosis (r=−0.44, P<0.0001)." (PMID 12671706, 2003). "The activation of EGFR has been shown to enhance tumour growth, invasion and spreading, and to inhibit apoptosis." (PMID 14583782, 2003). "The epidermal growth factor receptor (EGFR) family has been found to play a central role in tumour progression." (PMID 14520458, 2003). "When relating the LRIG1 and EGFR levels in tumour and kidney to each other, the ratio of EGFR/LRIG1 appeared high, especially in conventional RCCs." (PMID 14520461, 2003). "This novel finding in a human tumour specimen lends support to the suggestion that LRIG1 acts as a tumour suppressor and negative regulator of EGFR." (PMID 14520461, 2003). "AS-3 cells, expressing intermediate levels of EGFR, formed tumours of ∼1000 mm3 after 4 weeks post-implantation." (PMID 11953893, 2002). "Over the past decade, comprehensive data have been accumulated that strongly support a role for EGFR and its ligands in tumour development and growth." (PMID 11875748, 2002). "In the clinical setting, it will be important to define tumours whose growth is dependent on the EGFR and which are being driven by activating ligands such as TGFα and EGF." (PMID 11875715, 2002). "We used a panel of seven human head and neck cell lines with a wide range of EGFR expression representative of that found in human tumours." (PMID 11986789, 2002). "Control cells and antisense-EGFR transfected cells were injected into nude mice subcutaneously, and tumour volumes were measured for the duration of the experiments." (PMID 11953893, 2002). "PgR level was significantly inversely related to EGFR activity (r=−0.28, P=0.001) and tumour size (clinical, P=0.002, r=−0.21 and pathological P=0.013, r=−0.18)." (PMID 12085248, 2002). "Administration of an anti-mutant EGFR antibody to mice transiently reduced the growth rates of mutant tumours, confirming that the mutant receptor itself was important in this enhanced tumorigenicity." (PMID 11355942, 2001). "In situ hybridization on human colon tissue demonstrates that epidermal growth factor receptor (EGFR) mRNA expression is strongly increased during tumour progression." (PMID 9667648, 1998). "The immunoconjugates exert specific inhibition of EGFR expressing target cell proliferation and protein synthesis in in vitro assays and also inhibit the growth of grafted human tumour cells in nude mice." (PMID 9062402, 1997). "Overexpression of the epidermal growth factor receptor (EGFR) and ErbB-2 has been observed in a variety of human tumours, making these receptors promising targets for directed tumour therapy." (PMID 8826849, 1996). "Amplification and increased expression of many growth factor receptors, including the epidermal growth factor receptor (EGFR), has been observed in human tumours." (PMID 8956783, 1996). "The 5 year relapse-free survival was 77% for patients with EGFR- tumours compared with 24% for patients with EGFR+ tumours (P < 0.010)." (PMID 8883413, 1996). "In fact, the 5 year survival was 81% for patients with EGFR- tumours compared with 25% for patients with EGFR+ tumours (P < 0.0001)." (PMID 8883413, 1996). "One therapeutic strategy for overcoming EGF autocrine control of tumour growth is inhibition of EGFR protein tyrosine kinase (PTK)." (PMID 8956783, 1996). "No such association was observed between either c-erbB-2 or epidermal growth factor receptor (EGFR) expression in the original tumours and their in vivo tumour take." (PMID 7577462, 1995). "19A211 preferentially stained superficial tumours, and T43, T138 and EGFR preferentially stained invasive tumours." (PMID 7819039, 1995). "Primary tumours and cell lines expressed EGFR, showing higher basal level phosphotyrosine staining than erbB-2." (PMID 7599067, 1995).
tumor (continued). "The in vitro and in vivo stability and anti-tumour efficacy of the anti-EGFR/anti-CD3 bispecific monoclonal antibody (biMAb), M26.1, were analysed." (PMID 7547242, 1995). "This study suggests that most tumours have a latent potential to overexpress EGFR which is realised in tissue culture." (PMID 8080726, 1994). "Type 2 tumours displayed only allele loss on chromosome 10 (LOH 10), type 3 tumours had LOH 10 + LOH 17p and type 4 tumours contained LOH 10 + EGFR gene amplification." (PMID 7917918, 1994). "EGFR expression on the tumour cryosections was compared with expression on cryosections of skin and buccal mucosa." (PMID 8080726, 1994). "EGFR levels on some of the original tumours and xenografts of the cell lines were determined on cryosections by a competitive binding assay based on [125I]EGFR1, an EGFR-specific monoclonal antibody." (PMID 8080726, 1994). "Progression of superficial tumours, recurrence-free survival and survival were independently related to overexpression of EGFR in multivariate analysis." (PMID 7911031, 1994). "Serial cross-section studies have suggested that separate populations of ER+/EGFR- and ER-/EGFR+ cancer cells exist in tumours deemed by immunocytochemical assay (ICA) to be positive for both." (PMID 8198966, 1994). "A strong negative relationship was observed, with 26 of 88 (30%) bcl-2-positive tumours being EGFR positive, compared with 16 of 23 (70%) bcl-2-negative tumours being EGFR positive (P = 0.001), raising the possibility that bcl-2 is an ER-regulated gene." (PMID 8286195, 1994). "The xenografts expressed EGFR, as did the original tumours, even though they were derived from cell lines that displayed significant overexpression of EGFR." (PMID 8080726, 1994). "EGFR was overexpressed in 35% of cases and distinct nuclear localisation of EGFR positivity was found in 31% of the tumours." (PMID 7911031, 1994). "We have examined post-operative survival in 19 surgically treated patients with NSCLC who had full characterisation of EGFr on primary tumour membrane preparations from resection specimens." (PMID 8391303, 1993). "A statistically significant correlation was found between the maximum binding capacities of EGFR obtained from Scatchard plots and the percentage of positive tumour cells determined by MoAb EGFR1 (2P < 0.0001)." (PMID 1457340, 1992). "Overall 56% of tumours were EGFR-positive and the expression of EGFR was unrelated to axillary node status, tumour size and histological grade; and it was poorly associated with the tumour proliferative activity measured by Ki-67 immuno-cytochemistry." (PMID 1419645, 1992). "The binding characteristics of EGFr were similar in tumour and normal lung membranes (range of dissociation constant of high affinity sites: 0.1-0.6 nM)." (PMID 1654986, 1991). "A similar proportion of screened and unscreened tumours expressed c-erbB-2 oncoprotein and EGFR but expression of the oestrogen regulated protein cathepsin D was significantly more frequent in the screened group (P less than 0.05)." (PMID 1680369, 1991). "All 42 fresh tumour samples (five well differentiated; 28 moderately differentiated; nine poorly differentiated) expressed both EGFR and TFR to varying degrees." (PMID 2372483, 1990). "Tumours in which the staining intensity for both EGFR and TFR was intense invariably expressed the Ki-67 antigen in a high proportion of cells." (PMID 2372483, 1990). "Ten of these 20 tumours were EGFr+ (greater than 10 fmol mg-1 binding) and 9/13 patients progressing within six months had EGFr+ tumours." (PMID 3224082, 1988). "There was a significantly higher proportion of EGFr+ tumours in the endocrine failure group compared with the control population (P less than 0.001)." (PMID 3224082, 1988).
tumor (continued). "The epidermal growth factor receptor is homologous to the oncogene erb-beta and is the receptor for a class of tumour growth factors (TGF-alpha)." (PMID 3038157, 1987). "Using an unbiased high-content drug screen, we identified several small molecules that selectively inhibit LAPTM4B, and demonstrated that combination treatment with copanlisib and EGFR-TKIs produces robust anti-tumor effects in vitro and in vivo with negligible side effects." (PMID 41362742, 2026). "This study reveals that EGFR mutations prominently impaired dendritic cell (DC) maturation, disrupting their capacity to effectively prime CD8+ T cells and thereby compromising anti‐tumor immune responses." (PMID 41144813, 2026). "These collective findings led us to hypothesize that DCBLD1 promotes tumor growth through EGFR signaling modulation." (PMID 41522352, 2026). "For example, the use of proteolysis-targeting chimeras (PROTACs) to degrade EGFR L858R has been shown to downregulate PD-L1 and indoleamine 2,3-dioxygenase 1 protein levels, thereby amplifying anti-tumor immune responses and providing an approach to NSCLC immunotherapy." (PMID 41268614, 2026). "Thus, c‐Jun is likely a key transcriptional factor controlling EGFR‐mediated CD73 expression in EGFR mutant tumor cells." (PMID 41144813, 2026). "Albeit we tried to selectively study tumour‐derived EVs using either capturing with CSPG4‐antibody conjugated beads or by analysing the presence of EGFR T790M mutation in RNA in the EVs, we did not manage those verifications at this point." (PMID 41581122, 2026). "To address the challenges associated with EGFR-TKI resistance, we developed an ASO that reduces membrane cholesterol, inhibits invasion and resistance, and acts synergistically with cetuximab to achieve superior tumor inhibition." (PMID 41540015, 2026). "EGFR-004 overexpression significantly promoted EGFR phosphorylation in HN6 and CAL27 cells compared with the levels associated with EGFR-001 overexpression, a pattern also observed in the tumor tissues of nude mice." (PMID 41540015, 2026). "Via Tumor Immune Estimation Resource (TIMER), we next determined whether the EGFR mutation may influence the abundance of immune infiltrates (B cells, CD8+ T cells, CD4+ T cells, macrophages, neutrophils, and DCs)." (PMID 41144813, 2026). "Collectively, these results strongly indicated that EGFR mutation reshapes the phenotype of DCs toward an immature phenotype in both the TME and circulation, which may potentially impair anti‐tumor immunity." (PMID 41144813, 2026). "By targeting oncogenic drivers such as EGFR, adaptive mechanisms like Axl-driven EMT, immune checkpoints like PD-L1, and CSC-associated markers including CD133, these nanosystems can enhance tumor selectivity, improve drug accumulation, overcome resistance, and synergize with immunotherapy." (PMID 41560835, 2026). "Furthermore, EGFR overexpression resulted in increased cellularity in tumor-draining lymph nodes and reduced CD8+ T-cell representation." (PMID 41932901, 2026). "Previous studies suggest that an immunosuppressive tumor microenvironment (TME) might contribute to poor immune responses observed in EGFR-mutant LUAD 16-19." (PMID 41356800, 2026). "This system utilizes the targeting effect of the GE11 peptide with the epidermal growth factor receptor (EGFR) to accumulate at the tumor site, while the hydrazone bond serves as a pH-responsive linker that breaks in the acidic tumor microenvironment, triggering drug release." (PMID 42076148, 2026). "Notably, in this context, PD-L1 expression does not reliably predict benefit from ICIs but, rather, serves as a marker of aggressive tumor biology and early resistance to EGFR-TKI therapy." (PMID 41977474, 2026).
tumor (continued). "Recent studies have untangled that LPS can activate (EGFR) Epidermal Growth Factor Receptor signaling in (HSCs) Hepatic Stellate Cells, leading to the release of IL-8 from tumor cells and inducing angiogenesis, thereby accelerating the invasion and metastasis of HCC." (PMID 40990659, 2026). "Finally, we found that combining IL-6 and EGFR blockade effectively controlled pain and tumor growth simultaneously in SWN models." (PMID 41758723, 2026). "Additionally, after using the propensity score matching (PSM) method to eliminate the confounding effect of tumor stage on survival outcomes, Kaplan-Meier survival curves were plotted in EGFR-mutant NSCLC patients." (PMID 41539998, 2026). "The joint assessment of these variables could facilitate to more comprehensively reveal the biological characteristics of the tumour and predict a patient’s response to EGFR-TKI therapy." (PMID 41551443, 2026). "Therefore, the EP cell lines can serve as a reliable model to simulate tumor microenvironment of EGFR-mutant LUAD." (PMID 41356800, 2026). "This is in line with our findings, where the mutation’s identification suggests the potential for EGFR TKI therapy as a first-line treatment, as these therapies can block the constitutive activation of EGFR signaling, leading to reduced tumor proliferation and enhanced patient survival." (PMID 40740944, 2025). "Under the selective pressure of first- and third-generation EGFR-TKIs, tumor cells can adapt through on-target alterations (for example, T790M or C797S), as well as via bypass-track activation, such as MET amplification, HER2 or AXL upregulation, and reactivation of downstream signaling." (PMID 41472727, 2025). "Thus, resveratrol plays a crucial role in reversing tumor drug resistance by targeting drug transporters, down-regulating EGFR expression, and enhancing the efficacy of chemotherapeutic agents." (PMID 40490812, 2025). "Additionally, molecular docking studies were performed to explore the binding interactions of the complex with EGFR and VEGFR2, two key receptors implicated in tumor proliferation and angiogenesis." (PMID 41145684, 2025). "Both radiolabeled DARPins demonstrated EGFR-specific tumor uptake." (PMID 41226646, 2025). "Moreover, the immune response within the tumor microenvironment significantly influences the therapeutic efficacy of EGFR-TKIs." (PMID 40003951, 2025). "MIG-6 suppresses tumor growth by blocking EGFR and its downstream signaling pathways." (PMID 40535815, 2025). "La repetición de biopsias de tejido puede conllevar cierto riesgo, debido al estado clínico del paciente o a la localización del tumor, por lo que el análisis del plasma representa una alternativa más segura a la hora de evaluar el estado mutacional de EGFR durante el tratamiento." (PMID 40977824, 2025). "In addition, immune cell/ESCC PDO co-culture and in vivo models would be valuable resources to improve the efficacy of immune checkpoint inhibitors in EGFR-positive tumours." (PMID 40615716, 2025). "But considering the critical role of EGFR in tumor cell proliferation and survival, EGFR inhibitors may help prevent tumor recurrence or even inhibit the proliferation of undiagnosed micrometastases or the activation of dormant metastases." (PMID 41454126, 2025). "Notably, benzofuran‐pyrazole‐thiazolidinone, hydrazone, and isoxazolidine compounds have shown strong EGFR inhibition, effectively blocking downstream signaling cascades involved in tumor growth." (PMID 41523619, 2025). "In vivo, EGF released from KI-treated normal tissues together with KI-mediated unaltered EGFR expression in cancerous cells like SGC cells could drive tumor progression." (PMID 40508009, 2025).
tumor (continued). "Drug development focused on EGFR is a key area in anti-tumour research." (PMID 40172117, 2025). "Besides, the inhibitory effect of FH-EB02 on phosphorylated EGFR (p-EGFR) was considerably weaker even at 250 nM, indicating selective inhibition EGFR signaling in tumor cells co-expressing EGFR and B7H3." (PMID 41291854, 2025). "In contrast to normal brain, recurrent tumor cells also expressed wild-type EGFR." (PMID 40507329, 2025). "EGFR mutant tumours were shown to have increased genomic instability." (PMID 41509216, 2025). "CAP and sorafenib showed similar efficacies in reducing the tumor size, combining CAP and sorafenib reached the best efficacy in controlling tumor growth, and treating tumors harboring the EGFR(Y1068F) mutation with CAP showed the same therapeutic outcome as the control." (PMID 39781456, 2025). "One of the mechanisms contributing to resistance to EGFR TKIs, notably at diagnosis, is the amplification of the EGFR gene (EGFR-amp), leading to increased protein expression and activation of downstream signalling pathways that promote tumour growth and survival." (PMID 40149368, 2025). "Specific proteins on exosomes, such as epidermal growth factor receptor (EGFR), Ephrin type-A receptor 2 (EphA2) and Epithelial cell adhesion molecule (EpCAM), are increasingly used to distinguish between tumor-derived exosomes and non-tumor-derived exosomes." (PMID 40612948, 2025). "Although certain details, such as the transcriptional activation of PCBP2 by EGFR and the validation of the PCBP2-miRNA complex in OSCC patients, still lack direct evidence, this study represents a significant contribution to the ongoing topic of EGFR-driven tumor angiogenesis." (PMID 39816681, 2025). "Our study demonstrates that HB-EGF is highly expressed in SIP and, through its role as a ligand for EGFR, may drive a distinct proliferative pathway contributing to tumor growth." (PMID 41346909, 2025). "Thus, endeavors toward developing anti-EGFR therapies for GBM capable of specifically targeting the tumor-specific EGFRvIII must prevail to prevent native receptor recognition." (PMID 39940647, 2025). "DARPins binding to tumor-associated molecular targets such as human epidermal growth factor receptor 2 (HER2), epithelial cell adhesion molecule (EpCAM), epidermal growth factor receptor (EGFR), vascular endothelial growth factor (VEGF) and hepatocyte growth factor (HGF) have been described." (PMID 40445498, 2025). "Notably, we observed a significant increase in EGFR expression in tumor biopsies from NSCLC patients treated with RET inhibitors who experienced disease progression, further validating the clinical relevance of our findings." (PMID 40405293, 2025). "A plethora of growth factors is secreted by TAMs, such as epithelial growth factor (EGF), platelet-derived growth factor (PDGF), and epithelial growth ligands of the factor receptor (EGFR) family and basic fibroblast growth factor (bFGF), all stimulating tumor cell proliferation." (PMID 39996747, 2025). "In conclusion, our study developed a validated non-invasive model (RS-BTIplusVPE) by integrating multi-sequence radiomic model and VPE, which showed improved prediction of EGFR-TKI response in NSCLC patients with brain metastases compared to tumor-focused models." (PMID 40438144, 2025). "In parallel, circulating tumor DNA has emerged as a valuable tool for real-time monitoring of clonal evolution during therapy, capturing the dynamic emergence of acquired resistance and informing decisions such as anti-EGFR rechallenge." (PMID 40940901, 2025). "Discussion: We argue that EGFR mutations in each subgroup are immunologically different, which implies a distinct tumor microenvironment and might relate to the relatively high resistance of EGFR-positive tumors to immune checkpoint inhibitors." (PMID 40299444, 2025). "In addition, we performed a comparable functional assay on HeLa (EGFR+/B7-H6+) or SK-BR-3 (HER2+/B7-H6+) tumor cells." (PMID 39811682, 2025).